ARX (aristaless related homeobox)
Diseases named in the same sentence as ARX in open-access papers (continued):
Sharing a sentence is not in itself a finding about the gene and the disease.
Proud syndrome (4 papers, 2010 to 2024). "Noteworthily, one of the allelic disorders caused by ARX mutations is Proud syndrome, presenting as a main clinical features the agenesis of the corpus callosum." (PMID 34356104, 2021). "We investigated these and other missense mutations (R332P, R332H, R332C, T333N: associated with XLAG and Proud syndrome) predicted to affect the nuclear localisation sequences (NLS) flanking either end of the ARX homeodomain." (PMID 20148114, 2010).
XLAG syndrome (3 papers, 2014 to 2022). "A research study about the most frequent mutation found in the ARX gene suggests that the ARX gene is responsible for XLAG syndrome and milder forms of X-linked ID." (PMID 32858868, 2020). "Moreover, neuropathologic studies of the brain in newborn males affected with the XLAG syndrome (lack of ARX protein) show poorly delineated and atrophic basal ganglia and multiple small cavitations." (PMID 24528893, 2014).
autism spectrum disorder (2 papers, 2025). A spectrum of developmental disorders that includes autism, and Asperger syndrome. "Moreover, we confirmed that the disease variant associated with autism spectrum disorder, ARX A43V, also caused a 7.5-fold decrease in cooperativity." (PMID 41279221, 2025). "Additionally, we observed ectodermal EtOH-induced alterations in several genes, such as LHX2, SHANK2, TRIO, ZMYND8, ARX, NRXN3 and SEMA5A, that have also been associated with autism spectrum disorder (ASD) (SFARI Gene Database, 2024; accessed: 1, August, 2024)." (PMID 40401629, 2025).
Cognitive impairment (2 papers, 2007 to 2015). Abnormal cognition is characterized by deficits in thinking, reasoning, or remembering. "This is one of the three hot spot regions for X-linked mental retardation containing ARX, a gene prominently mutated in both syndromic and non syndromic cognitive impairments." (PMID 17480217, 2007). "ARX gene represents a hot spot for mutations in families with cognition disorders because its mutations account for 9.5% of X-linked MR families." (PMID 17480217, 2007).
diabetes (2 papers, 2016 to 2021). "In this manuscript, we investigated expression patterns of 3 TFs with known changes in islet cell development and diabetes: α cell–specific ARX, β cell–specific MAFA, and MAFB, which is expressed in both α and β cells and has a unique expression profile compared with rodent islets." (PMID 34428183, 2021). "Our findings suggest that ARX inhibition may contribute to redifferentiation of expanded human BCD cells, as part of an approach for β-cell replacement therapy of diabetes based on ex-vivo expansion of islet cells from individual donors for transplantation into multiple recipients." (PMID 26856418, 2016).
Dyskinesia (2 papers, 2011 to 2024). A movement disorder which consists of effects including diminished voluntary movements and the presence of involuntary movements. "A certain number of them have been associated with dyskinesia and neurological disorders including phenotypes observed in ARX-mutated patients." (PMID 21966449, 2011).
infantile epilepsy (2 papers, 2015 to 2024). "Pathogenic variants in ARX cause a pleomorphic syndrome that includes infantile epilepsy with a variety of movement disorders ranging from focal hand dystonia to generalized dystonia with frequent status dystonicus." (PMID 38711225, 2024). "Molecular screening of ARX gene is frequent in patients with XLID, ID presenting with infantile epilepsy or movement disorder or brain and genital malformations." (PMID 26029707, 2015).
metastatic disease (2 papers, 2020). "All metastatic tumors expressed ARX, two also expressed PDX1 (double positive)." (PMID 31846235, 2020).
Rett syndrome (2 papers, 2018 to 2023). A severe neurodevelopmental disorder affecting the central nervous system.
tuberous sclerosis (2 papers, 2018 to 2025). Hereditary disease characterized by seizures, intellectual disability, developmental delay, and skin and ocular lesions. "The syndrome is classified into symptomatic, idiopathic, and cryptogenic forms, based on underlying causes such as brain trauma, malformations, infections, chromosomal abnormalities (e.g., Tuberous Sclerosis Complex), or genetic mutations in genes like ARX and CDKL5." (PMID 41357344, 2025). "Around 70%–75% of cases have an identifiable cause, which can include brain trauma, malformations, infections, chromosomal abnormalities like Tuberous Sclerosis Complex (TSC), or mutations in genes like Aristaless-related homeobox (ARX) or cyclin-dependent kinase-like 5 (CDKL5)." (PMID 41357344, 2025).
type 1 diabetes (2 papers, 2016 to 2021). "In type 1 diabetes patients, alpha cells have reduced expression of ARX and increased expression of NKX6.125." (PMID 34493754, 2021). "The combination of RC and ARX shRNA treatment may facilitate the generation of abundant insulin-producing cells for transplantation into patients with type 1 diabetes." (PMID 26856418, 2016).
Aicardi syndrome (1 paper, 2023). Aicardi syndrome is a rare neurodevelopmental disorder defined by the triad of agenesis of the corpus callosum (total or partial), typical chorioretinal lacunae and infantile spasms that affect almost exclusively females. "The diagnosis of a patient referred with Aicardi syndrome was changed to DEE1 on discovery of a structural variant in ARX (see SV section above)." (PMID 37946251, 2023).
apraxia (1 paper, 2014). Apraxia is a neurological disorder characterized by the inability to perform tasks or movements, despite having the desire and physical ability to perform them. "The ARX c.429_452dup24 mutation may be a developmental model for Limb Kinetic Apraxia." (PMID 24528893, 2014).
colorectal cancer (1 paper, 2021). A primary or metastatic malignant neoplasm that affects the colon or rectum. "Two CpGs at which the effect of age on DNA methylation was different in males and females (at the TMEM49 and ARX loci) were associated with survival of all cancers and colorectal cancer, respectively." (PMID 33919912, 2021). "There was one age-by-sex-related CpG (cg21729122) in the TSS1500 region of ARX (X chromosome) that was associated with survival of colorectal cancer with HR = 1.59 (95% CI: 1.28–1.97), p = 2.3 × 10−5 in Model 4.1 and HR = 1.52 (95% CI: 1.22–1.89), p = 1.8 × 10−4 in Model 4.2." (PMID 33919912, 2021). "Our study suggests that blood DNA methylation at cg21729122, located in the TSS1500 region of ARX, may be associated with sex-specific survival from colorectal cancer." (PMID 33919912, 2021).
endometrial cancer (1 paper, 2023). Primary or metastatic malignant neoplasm involving the endometrium (mucous membrane that lines the endometrial cavity). "Among candidate genes, ARX, POU2F3, TLX2 and LIM1 were derived as molecules contributing to the malignant transformation of endometrial cancer." (PMID 36969081, 2023).
gangliocytoma (1 paper, 2025). A well differentiated, slow growing neuroepithelial neoplasm composed of neoplastic, mature ganglion cells. "In 2 composite gangliocytoma/NETs (CoGNETs), the NET component expressed PP, and both NET and ganglion cells expressed ARX." (PMID 40553402, 2025).
Hypoglycemia (1 paper, 2018). A decreased concentration of glucose in the blood. "For example, an early-onset loss of pancreatic α cells and a concomitant increase in β cells is observed in mice carrying an aristaless-related homeobox (Arx) mutation, resulting in severe hypoglycemia and neonatal death." (PMID 29880854, 2018).
leukodystrophy (1 paper, 2023). Leukodystrophies are a group of rare, progressive, metabolic, genetic diseases that affect the brain, spinal cord and often the peripheral nerves. "We focused on the involvement of ARX in 4H leukodystrophy because of its role in cortical development and its association with other disorders." (PMID 36729681, 2023).
pancreatic NEN (1 paper, 2025). "Detailed characterization of pulmonary NEC, pulmonary carcinoid, pancreatic NEN, ileal NEN, and MiNEN was performed using immunohistochemical staining to detect pan-cytokeratin (panCK), Thyreoglobulin (TG), Calcitonin (CT) and the transcription factors CDX2, SATB2, TTF1, GATA3, ARX and PDX1." (PMID 41145514, 2025).
pancreatic tumors (1 paper, 2022). "Our present survival analysis suggests that high ARX expression is favorable for PAAD patients, which might suggest a subtype-specific behavior that is worth investigation since pancreatic tumors arising from endocrine or epithelial portion have different properties." (PMID 35361846, 2022).
serous cystadenoma (1 paper, 2019). A serous neoplasm in which the cysts and papillae are lined by a single layer of cells without atypia, architectural complexity or invasion. "Both ARX and FCN1 had a very low level of expression in samples of FTE, OEI, serous cystadenoma, SBT, and LGSC, but highly expressed in OSEs." (PMID 30949203, 2019).
viral infection (1 paper, 2020). "In contrast, α-cell-specific transcripts including GCG, ARX, BAMBI, DPP4, and POU6F2 were not affected by infection, which corresponded with our observation that viral infection was infrequent in α cells." (PMID 32093375, 2020).
X-linked deafness (1 paper, 2024). "First, some X-linked deafness genes were not included in the predefined panel containing 227 HL-related genes, such as RPS6KA3, EFNB1, HDAC8, ARX, and ANOS1, which may cause a negative molecular diagnosis for some patients." (PMID 39272213, 2024).
tumor (12 papers, 2013 to 2025). "Indeed, in the intermediate-WT group we observed the presence of ARX+ tumours, with high risk of relapse." (PMID 33288854, 2020). "Notably, all the DAXX/ATRX-negative samples expressed ARX, confirming the α-like tumour susceptibility for these mutations." (PMID 33288854, 2020). "When ALT and ARX were evaluated together, remarkably, relapse was found in every ARX+/ALT+ tumor, while it occurred less frequently in all other subgroups." (PMID 34069193, 2021). "While only a subset of ARX+ tumours secreted glucagon (n = 7, 20% of all the ARX+ tumours), almost all the PDX1+ tumours produced insulin (n = 18, 95% of all PDX1+ tumours)." (PMID 33288854, 2020). "Although focal nesidioblastosis was considered as explanation for ARX expression, it was deemed highly unlikely due to the characteristic tumor morphology, random peptide hormone expression, and the presence of metastases." (PMID 32103422, 2020). "They do express ARX and are characterized by large tumor size (3.5–9 cm) and metastatic behavior." (PMID 37152923, 2023). "If an ALT+/ARX+ tumor is identified in the liver, this would not only indicate early that the unknown primary lesion is a PanNET but also that it is likely to be amenable to surgery." (PMID 34069193, 2021). "Additionally, while PDX1 expression appears to be specific for benign and low stage tumours, ARX expression is retained at early and at advanced stages and only DAXX/ATRX status provides more information about stage and risk of disease progression." (PMID 33288854, 2020). "Consistent with our enrichment analysis, transcription factors essential for EEC differentiation—such as NEUROD1 and Aristaless-related homeobox (ARX)—were downregulated in both the murine and human tumor microenvironments (TMEs)." (PMID 41303610, 2025). "All neoplasms were investigated with immunohistochemistry for neuroendocrine markers (Synaptophysin, Chromogranin-A), ATRX, DAXX, ARX, and PDX1 transcription factors." (PMID 39331358, 2024). "We scored nuclear positivity for ARX in 34 samples (52%), for PDX1 in 21 samples (32%), 3 tumours (5%) showed strong double positivity and 13 (20%) were negative for both TFs." (PMID 33288854, 2020). "Overall, using a representative surgical specimen tumor block as reference standard, 85% of the cytology cases (11/13 correct) were accurate in determining tumor transcription factor subtype (ARX+/PDX1−, ARX−/PDX1+, ARX+/PDX1+, ARX−/PDX1−)." (PMID 31846235, 2020). "Concordance between cytologic and surgical specimens for ARX protein expression was 100%, whereas concordance for PDX1, ALT, and WHO tumor grade was 85%, 91%, and 73%, respectively." (PMID 31846235, 2020). "A group of 4 genes (ARX, GPR17, LHX2 and CXCL14) well stratified LGGs between infratentorial and supratentorial tumours." (PMID 23947815, 2013). "In the non‐metastatic tumors 12 out of 15 had ARX expression of which 2 were double positive, while 2 tumors had sole PDX1 expression and 1 tumor had no ARX or PDX1 expression (double negative)." (PMID 31846235, 2020). "Of the intermediate-WT tumours for which IHC data were available (n = 6), two were positive for PDX1, two for ARX and two were negative for both TFs." (PMID 33288854, 2020). "A minority of intermediate tumours (4/44, 9%) were negative for both PDX1 and ARX." (PMID 33288854, 2020).
neurological disorders (11 papers, 2007 to 2025). "The data in this report further support an emerging body of evidence that one transcription factor, in this case ARX, has unique roles in different progenitor cells and that these distinguishable functions can be associated with specific neurologic disorders." (PMID 28103279, 2017). "Mutations in ARX are associated with a spectrum of neurologic disorders and experimental studies indicate that ARX plays distinct roles in different neural progenitor populations." (PMID 28103279, 2017). "In humans, mutations of ARX result in a spectrum of neurologic disorders, the most severe clinical presentation being X-linked lissencephaly associated with abnormal genitalia (XLAG)." (PMID 24236044, 2013). "The present study by itself cannot exclude the possibility that the islet phenotype is secondary to neurological disorder caused by defective ARX function." (PMID 23671715, 2013). "Mouse models of XLAG, ISSX and other human ARX mutations demonstrate a direct genotype-phenotype correlation in ARX-related neurologic disorders." (PMID 24236044, 2013). "Moreover, a P26L missense variant in ARX has been associated with neurological disease, suggesting this Paired-like to ANTP HD swap disrupts protein function." (PMID 41279221, 2025). "Aristaless Related Homeobox mutations can lead to severe neurological diseases, including X-linked intellectual disability, epilepsy, as well as structural brain malformations (Friocourt and Parnavelas, 2010), and these mutations have been studied extensively using mouse models." (PMID 35546872, 2022). "One of those genes is Aristaless related homeobox (ARX) encoding a polyA-rich homeobox transcription factor essential for cerebral patterning and its mutations cause different neurologic disorders." (PMID 17480217, 2007).
neurodevelopmental disorder (8 papers, 2015 to 2024). A behavioral and cognitive disorder with onset during the developmental period that involves impaired or aberrant development of intellectual, motor, or social functions. "Variants in the aristaless-related homeobox (ARX) gene cause a diverse spectrum of phenotypes of neurodevelopmental disorders (NDD) in male patients." (PMID 36845779, 2023). "With this in mind, we therefore conclude that perturbations of long-range activity of ARX/Arx ultraconserved enhancers could have dosage-sensitivity-driven effects, and thus, constitute a risk for neurodevelopmental disorders." (PMID 35328505, 2022).
brain disorder (1 paper, 2023). A disease affecting the brain or part of the brain. "ARX mutations are associated with several brain disorders, and ARX loss of function is associated with abnormal cortical interneuron development and migration." (PMID 36729681, 2023).
cancer (1 paper, 2021). A tumor composed of atypical neoplastic, often pleomorphic cells that invade other tissues. "Methylation at two CpGs overlapping TMEM49 and ARX genes was associated with survival of overall (HR = 0.91, p = 7.7 × 10−4) and colorectal (HR = 1.52, p = 1.8 × 10−4) cancer, respectively, with significant age-by-sex interaction." (PMID 33919912, 2021).
genetic disorders (1 paper, 2022). "Differs from the high-frequency genes, other causative genes (ARX, SCN2A, etc.)were only found in <3% of the cases with genetic disorders, respectively." (PMID 35330882, 2022).
ARX also shares sentences with these, for which no sentence is quoted: infantile epileptic encephalopathy (3 papers); infection (3); movement disorder (3); developmental and epileptic encephalopathy (2); Dravet syndrome (2); hydranencephaly (2); Macrogyria (2); Miller-Dieker syndrome (2); oculopharyngeal muscular dystrophy (2); spinal muscular atrophy (2); 22q11.2 deletion syndrome (1); Angelman syndrome (1); Ataxia (1); Blepharophimosis (1); channelopathies (1); Choreoathetosis (1); Coffin-Lowry syndrome (1); congenital central hypoventilation (1); cryptorchidism (1); double cortex syndrome (1); Duchenne muscular dystrophy (1); Dysarthria (1); early infantile epileptic encephalopathy 1 (1); EARS disease (1); esophageal squamous cell carcinoma (1); focal dystonia (1); fragile X syndrome (1); generalized dystonia (1); holoprosencephaly (1); holoprosencephaly type 5 (1).
A further 18 diseases each share a sentence with ARX in 1 paper.